CRP (C-reactive protein)
Diseases named in the same sentence as CRP in open-access papers (continued):
Sharing a sentence is not in itself a finding about the gene and the disease.
tumor (continued). "Inflammation-related markers, such as interleukin-6 and C-reactive protein, which are often elevated in frail individuals, are also known to promote tumor progression and metastasis." (PMID 40684433, 2025). "Multivariable adjustment: Incorporating clinical covariates (e.g., CRP levels for inflammation, tumor histology for heterogeneity) into regression models to isolate the independent effect of MTV/TLG." (PMID 40276059, 2025). "Elevated CRP indicates the presence of a persistent inflammatory state, which can promote tumor growth and metastasis by enhancing angiogenesis, supporting tumor cell survival, and increasing invasiveness." (PMID 40823074, 2025). "The variable importance plot identified key features influencing survival predictions, including CRP, Child-Pugh classification, M status, HSP90α, and tumor number." (PMID 41458972, 2025). "The two groups were compared in terms of age, preoperative nutritional intervention, BMI, smoking, drinking, TNM staging, tumor differentiation, intraoperative blood transfusion, albumin, hemoglobin, prealbumin, C-reactive protein, and WBC." (PMID 40589635, 2025). "The CRP level of 10 mg/L in the T+AI group surpassed that in the T group (p = 0.047), and the tumor bed was significantly larger in the T+AI group, demonstrating statistical significance between the 2 groups (p=0.025)." (PMID 40879489, 2025). "The phase 3 OAK trial, which compared atezolizumab with docetaxel in NSCLC, the CRP flare was predictive of improved survival only in the immunotherapy arm, supporting its potential as a tumor-agnostic, immunotherapy-specific marker." (PMID 41200168, 2025). "Patients with low CALLY scores were significantly more likely to have elevated CRP (p < 0.001), lower albumin (p < 0.001), reduced lymphocyte counts (p < 0.001), and higher tumor markers (CEA and CA19-9, both p < 0.001 and p = 0.001, respectively)." (PMID 41517561, 2025). "C-reactive protein, a hepatocyte-derived acute-phase reactant, mediates tumor progression by facilitating the establishment of chronically inflamed microenvironments." (PMID 40563367, 2025). "Interleukin-6(IL-6), produced by the tumor or surrounding cells, stimulates the liver to produce acute-phase response proteins (such as CRP and fibrinogen), both in the fasted and fed states." (PMID 40004975, 2025). "However, it remains unclear whether elevated CRP is a symptom of the tumor or a causative factor." (PMID 41179937, 2025). "Multivariate analysis showed that tumor size, general condition, histological type, and pre-treatment C-reactive protein (CRP) value had a significant impact on OS results." (PMID 41374960, 2025). "In NSCLC, preoperative serum CRP levels correlate significantly with tumor invasive characteristics and histological malignancy grade, serving as an adjunctive biomarker to improve early diagnostic accuracy." (PMID 40563367, 2025). "Subsequently, stepwise Cox regression analysis identified Age, CRP, HSP90α, Child–Pugh class, tumor number, M status, and PVTT as the final independent prognostic factors for OS." (PMID 41458972, 2025). "Postoperatively, closer surveillance (e.g., more frequent imaging) is advised for patients with high-risk features, such as persistently elevated CRP, abnormal tumor markers, or LVI/PNI/tumor budding." (PMID 40277783, 2025). "At the time of diagnosis, elevated CRP level reflects tumor aggressiveness, such as larger tumor size, more advanced stage, higher grade, or the presence of distant metastasis." (PMID 40416620, 2025). "For example, CRP can impede the differentiation and effector functionalities of T cells, thereby diminishing the body’s anti-tumor immune response and creating a conducive environment for tumorigenesis." (PMID 39980561, 2025). "Systemic inflammation markers-including NLR, C-reactive protein (CRP), and lactate dehydrogenase (LDH)-are increasingly recognized as prognostic indicators in NSCLC, reflecting tumor-associated inflammation and metabolic dysregulation." (PMID 41451214, 2025).
tumor (continued). "LASSO and stepwise Cox regression identified age, CRP, HSP90α, Child-Pugh classification, tumor number, metastatic (M) status, and portal vein tumor thrombosis (PVTT) as independent prognostic markers." (PMID 41458972, 2025). "Our study proposes the CRAFITY-100 RULE, which integrates baseline inflammatory and tumor markers (CRP, AFP, PIVKA-II) with their early kinetic changes, to better stratify patients with unresectable HCC undergoing immunotherapy." (PMID 41008900, 2025). "Elevated CRP levels reflect systemic inflammation driven by neuroendocrine factors, which are known to contribute to an immunosuppressive tumor microenvironment." (PMID 41458972, 2025). "Laboratory tests demonstrated elevated C-reactive protein (4.75 mg/dL), but some tumor markers (including CEA, CA19-9, and CA125), anti-nuclear antibodies, MPO-ANCA, PR3-ANCA, β-D-glucan, and interferon-gamma release assay were all negative." (PMID 40870884, 2025). "​In addition, the absence of correlation between inflammation marker dynamics (including CRP trend) and best overall response or tumor regression percentage aligns with emerging understanding of immunotherapy." (PMID 41267986, 2025). "Serum C‐reactive protein (CRP) and tumor size correlated moderately positively with both serum and tissue BHB levels." (PMID 39545923, 2025). "Recent studies have identified that the combination of high CRP and low LMR is associated with worse clinical outcomes in various conditions, including chronic inflammatory diseases and neoplasms." (PMID 41171774, 2025). "Future studies should explore the integration of inflammatory markers (e.g., CRP, IL-6), tumor-intrinsic features, or functional immune assays to enhance prediction accuracy in chemotherapy-treated patients." (PMID 40958865, 2025). "Key inflammatory mediators, such as interleukin-6, C-reactive protein and tumour necrosis factor-α, are discussed in the context of their dual role in tumour progression and atherogenesis." (PMID 41235913, 2025). "Subsequently, stepwise Cox regression analysis was performed, and the final independent prognostic factors were determined to be Age, CRP, HSP90α, Child, Tumor number, M status, and PVTT." (PMID 41458972, 2025). "Conversely, the positive relationship between CRP and tumor budding in male patients is consistent with the known pro‐inflammatory role of CRP." (PMID 40985344, 2025). "The inflammatory response can vary greatly between individuals, and factors such as preoperative inflammation (due to the tumor or chronic lung disease) can elevate baseline CRP and cloud postoperative interpretation." (PMID 41153812, 2025). "Postoperative VEGF levels on day 7, postoperative endocan levels on day 1, and preoperative CRP levels differed significantly between the groups according to histopathological tumor classification (p values: 0.034, 0.041, and 0.045, respectively)." (PMID 41509932, 2025). "Our study showed a statistically significant increase in CRP levels with positive expression of hormones (estrogen and progesterone) as well as low proliferative activity and high tumor differentiation." (PMID 40699615, 2025). "In NMIBC, elevated CRP levels are thought to worsen systemic inflammation, impair immune responses, and contribute to tumour progression." (PMID 40485741, 2025). "The direction of effect was similar for Grade 1 and Grade 2/3 tumours, but with the exception of CRP and GPS 2 versus 0, differences were significant only in higher grade tumours." (PMID 38477040, 2025). "Elevated levels of such common inflammatory factors as TNF-a, CRP, and IL-6 indicate increased tumor activity and higher malignancy, which can exacerbate the patient’s condition." (PMID 40621513, 2025). "By activating the complement system and promoting the recruitment of immune cells to the tumor microenvironment, CRP plays a role in amplifying the inflammatory response." (PMID 40926779, 2025).
tumor (continued). "The integration of these findings with the updated CRP interactome further underscores the potential link between CRP and tumor cell metabolism." (PMID 41614767, 2025). "It is worth noting that AE can decrease pro-inflammatory cytokines in the tumor microenvironment, such as TNF-α, IL-6, and CRP, by modulating immune system responses, and these cytokines play a promoting role in tumor progression." (PMID 41480347, 2025). "C-reactive protein (CRP), a key marker of systemic inflammation, is strongly associated with advanced tumor stage, therapy resistance, and poorer survival outcomes in HGGs." (PMID 41346390, 2025). "In patients with neoplasms, fibrinogen and CRP were significantly lower at T2 versus T0 (p = 0.006/p < 0.001)/T1 (p = 0.041/p = 0.049) and at T1 versus T0 for CRP (p = 0.049), while fibrinogen did not have a significant evolution from T0 to T1 (p = 0.286)." (PMID 41153844, 2025). "The reduction in lymphocyte count and the elevated CRP levels leading to a lower CRP‐to‐Lymphocyte ratio (CLR) indicate a pro‐tumor inflammatory state and impaired antitumor immune function." (PMID 40716028, 2025). "In the univariate analysis, the following variables were identified as significant predictors of PFS: NLR (p = 0.01), PLR (p = 0.011), MLR (p = 0.001), SII (p = 0.008), PIV (p < 0.001), CRP (p = 0.021), albumin (p = 0.021), and tumor size (p = 0.004)." (PMID 39851955, 2025). "Elevated levels of CRP enable the formation of a tumor microenvironment that is conducive to sustained tumor growth, invasion, and metastatic conditions." (PMID 40642165, 2025). "Three clinical features (C-reactive protein, baseline tumor size, and programmed death receptor ligand 1) and seven radiomics features (one first-order feature and six texture features) were selected for the model." (PMID 41487592, 2025). "An increase in the CRP level was also noted with high and medium degrees of tumor differentiation and a low proliferative activity index." (PMID 40699615, 2025). "The interleukin-6, tumor necrosis factor-alpha, and C-reactive Protein (CRP) were found to be related to tumor progression." (PMID 40806823, 2025). "For instance, CRP has been shown to have elevated levels that correlate positively with tumour status." (PMID 40076898, 2025). "While AFP reflects tumor burden and immune evasion, CRP serves as a proxy for systemic inflammation—two critical biological dimensions that impact immunotherapy responsiveness." (PMID 41358154, 2025). "Other biomarker classes, including TNF-receptor signaling, CRP and systemic inflammation indices (NLR, SII, and PIV), IGF-1, CD markers, tumor-associated antigens, and BDNF, were likewise inconsistently related to cognition." (PMID 41228315, 2025). "Increased levels of inflammatory markers such as neutrophils, CRP, CRP/Alb, and composite indices like NLR, PLR, SIRI, and SII have been associated with more aggressive tumor behavior, immunosuppressive tumor microenvironment, and limited therapeutic efficacy." (PMID 40943444, 2025). "As the most sensitive acute phase protein (APP) in dogs, CRP can be a marker of inflammation triggered by injuries, infections, stress, or neoplasia." (PMID 40427378, 2025). "Other tumor‐related parameters including Cancer Antigen 15‐3 (CA 15‐3), Iron (Fe), C‐Reactive Protein (CRP) and the complete blood count (CBC) were also assessed." (PMID 40791284, 2025). "The relevant variables were patient-related (sex, age, body mass index, American Society of Anesthesiologists (ASA) score, previous abdominal surgery, and C-reactive protein) and tumor-related (malignancy, tumor size, and tumor site)." (PMID 39860037, 2025). "In multivariate Cox regression analyses, AFP, ECOG performance status, Child-Pugh score, and intrahepatic tumor size, PBIShi, NLR, and CRP were associated with OS." (PMID 40568585, 2025).
tumor (continued). "SCLC exhibits a unique tumor microenvironment characterized by neuroendocrine features and elevated IL-6 signaling, which drives CRP production and immunosuppression." (PMID 41267986, 2025). "Laboratory assessments included serum levels of tumour markers, inflammatory markers such as CRP, and key hemostatic parameters, including thrombocyte count, prothrombin time (PT), activated partial thromboplastin time (aPTT), and fibrinogen levels." (PMID 40332145, 2025). "Although the percentage of elevated ADAM15 concentration was lower than for classical tumor markers such as CEA and CRP, its diagnostic value notably increased when used in combination." (PMID 40725774, 2025). "From this broad prognostic spectrum, we identified three core clinical variables—CRP, baseline tumor size (BTS), and PD-L1 expression—to construct a streamlined clinical model." (PMID 41487592, 2025). "Chronic systemic inflammation, as indicated by elevated CRP, plays a crucial role in shaping the tumor microenvironment by promoting angiogenesis, epithelial–mesenchymal transition (EMT), and metastatic spread." (PMID 40565984, 2025). "In contrast, the HELPP score integrates not only laboratory markers (CRP, albumin, platelet count) but also tumor markers (CEA, CA19-9) and the ASA physical status score, thereby offering a broader assessment of both oncologic and clinical status." (PMID 41517561, 2025). "CRP has been associated with cancer-related inflammation and poor outcomes, whereas LDH reflects tumor metabolism and burden, with an elevated LDH level recognized as an unfavorable prognostic factor for CRC." (PMID 41340164, 2025). "The input features were age (mean age = 52.8 years), BMI (mean = 26.2 kg/m2), frailty score (mean = 2.7), CCI (mean = 3.1), tumor volume (mean tumor volume = 19.6 cm3), type of surgical access, and inflammatory markers (CRP and ESR)." (PMID 40809627, 2025). "The liver, involved in the Cori cycle producing glucose de novo from tumor-derived lactate, prioritizes the synthesis of acute-phase proteins—such as C-reactive protein (CRP) and fibrinogen—at the expense of albumin and transferrin." (PMID 41007303, 2025). "For example, the prognostic weight of CLR is conceptually consistent with the well-documented roles of its components: CRP, an acute-phase reactant driven by pro-inflammatory cytokines like IL-6, and lymphocytes, essential for adaptive anti-tumor immunity." (PMID 41451214, 2025). "CRP has emerged as a significant post–first treatment factor, emphasizing the impact of inflammatory processes caused by HAIC, such as cell damage in tumor and stromal cells." (PMID 41429572, 2025). "The NF-κB signaling pathway activates proinflammatory signals (such as TNF) through IL17RE and CRP, thereby promoting tumor growth in an inflammatory environment." (PMID 40989695, 2025). "Patient characteristics, including age, sex, body mass index, serum albumin, C-reactive protein, tumor markers, prognostic nutritional index (PNI), modified Glasgow prognostic score (mGPS), and geriatric nutritional risk index (GNRI), were also analyzed." (PMID 39410049, 2024). "The effect of CRP on tumor progression needs to be examined in in vivo models, such as the tumor‐bearing mouse model; however, this remains challenging." (PMID 39564003, 2024). "The potential usefulness of the CRP/Alb as a biomarker has been highlighted in various tumours, such as digestive system tumours and gynaecological carcinomas." (PMID 38496751, 2024). "Pre-operative tumor marker levels and inflammatory markers [C-reactive protein - CRP, albumin, absolute neutrophil count (ANC), absolute lymphocyte count (ALC), absolute platelet count (APC)] and patient history were retrieved using MedSolution database." (PMID 38645565, 2024). "If we summarize the data of our cohort until this point, we can say that patients who had an elevated preoperative CRP level had a bigger tumor (>pT2), a higher grading (>G3), and a poorer prognosis." (PMID 39001318, 2024).
tumor (continued). "Concurrently, research indicates that CRP directly impairs the functionality of immune‐active cells, diminishing the body's cytotoxic immune response and consequently facilitating tumor immune escape." (PMID 39641241, 2024). "This IL1–IL6 cycle intensifies systemic inflammation (e.g., increasing C-reactive protein) and shapes a tumor-promoting environment by recruiting immune-suppressive cells and fostering angiogenesis, aiding tumor survival and immune evasion." (PMID 39766086, 2024). "Lactate dehydrogenase (LDH), a surrogate marker of tumor infiltration, and the general inflammatory markers C-reactive protein (CRP) and ferritin all shared a connection with severe CRS and/or ICANS." (PMID 38329486, 2024). "Blood tests including complete blood count, bone profile, erythrocyte sedimentation rate, C-reactive protein, rheumatoid factor, antinuclear antibodies, and tumour markers were normal." (PMID 38983111, 2024). "There was a significant association between high CRP levels and BRAF-mutated tumours in the U-CAN validation cohort." (PMID 39613865, 2024). "In its monomeric form (mCRP), CRP activates inflammatory mechanisms by interacting with cell membranes and immune cells, aiding initial defence against tumours and creating a carcinogenic environment." (PMID 39498386, 2024). "Positive significant correlations were observed between tumor size and pre-T leukocytes, neutrophil granulocytes, immature granulocytes, and CRP levels." (PMID 39199602, 2024). "In our previous studies, we analyzed the diagnostic and prognostic value of CRP and IL-6 levels measurement in OC in relation to different histological subtypes (OSCC and OAC) and compared them with classical tumor markers: CEA and SCC-Ag." (PMID 38673838, 2024). "Thirteen patients (50%) experienced pain due to the tumor, and the mean CRP level was 2.3 mg/dL in this analysis." (PMID 38730358, 2024). "High expression of exosomal lncRNA-ATB and miRNA-21 correlated with worse outcomes for these patients, as well as larger tumor size and increased C-reactive protein levels, suggesting that these two ncRNAs have prognostic value in HCC." (PMID 39585046, 2024). "High CRP levels often indicate an immunosuppressive tumor microenvironment, and CRP can induce the infiltration of M2 macrophages and regulatory T cells and inhibit the proliferation and function of CD4+ and CD8+T cells." (PMID 39555053, 2024). "When elevated CRP levels are found, OSCC patients with larger tumors and more advanced tumor stages have a lower overall survival rate; thus, elevated CRP levels can be considered a prognostic parameter." (PMID 38910781, 2024). "When stratifying for MSI status in the U-CAN validation cohort, a high CRP level indicating poor prognosis was mainly seen in patients with an MSS tumour." (PMID 39613865, 2024). "Associations were found between high CRP levels (SIR) and MSI tumours as well as an increased local anti-tumour immune response." (PMID 39613865, 2024). "CRP, a widely available biomarker, has been studied in other protocols for its ability to provide information about tumor prognosis." (PMID 38877146, 2024). "Visceral fat area emerged as an independent predictor of recurrence-free survival, C-reactive protein, Fuhrman nuclear grade, tumor size and microvascular invasion." (PMID 38730649, 2024). "Higher levels of pks+E. coli were associated with decreased serum CRP levels and reduced densities of CD4+ cells and CD163+ cells in the tumor-immune microenvironment." (PMID 39272861, 2024). "For instance, elevations in tumor-secreted inflammatory cytokines such as interleukin (IL)-1β, IL-6, C-reactive protein (CRP), and tumor necrosis factor (TNF)-α trigger systemic inflammation and activation of skeletal muscle catabolic pathways." (PMID 40443828, 2024). "Via the FcγRIIb-p38MAPK-ROS signaling pathway, C-reactive protein (CRP) can also attenuate the anti-tumor response." (PMID 38473328, 2024).